FTO (FTO alpha-ketoglutarate dependent dioxygenase)
Diseases named in the same sentence as FTO in open-access papers (continued):
Sharing a sentence is not in itself a finding about the gene and the disease.
Obesity (continued). "Among the four ethnic groups (Chinese, Caucasian, African-Americans and Hispanic populations), we found that 35 SNPs in intron 1 of FTO gene were significantly associated with indicators of obesity in Caucasians." (PMID 24879436, 2014). "The FTO rs9939609 polymorphism, one of the SNPs that were reported, has been associated with obesity, metabolic syndrome, insulin resistance, type 2 diabetes mellitus and cardiovascular disease." (PMID 25367448, 2014). "So far the data about the association of FTO with obesity in adolescents of southern Han Chinese was limited, the samples of our study were randomly selected from Wuxi (southern city of China)." (PMID 24911064, 2014). "Multitudinous studies have associated FTO polymorphisms with obesity in different European populations." (PMID 24911064, 2014). "In 2007, genome-wide association studies (GWAS) led to the discovery of single nucleotide polymorphisms (SNPs) in FTO, which incurred an increased risk of obesity." (PMID 24503721, 2014). "To determine if the effect of genetic variants differed by sex, we stratified by sex and found that 25 FTO SNPs were specifically associated with obesity in females only." (PMID 24879436, 2014). "Although the variant found in the FTO locus clearly showed association with BMI, the function of this gene in relation to obesity was unclear at the time." (PMID 24719615, 2014). "Single nucleotide polymorphisms in the first intron of the fat-mass-and-obesity-related gene FTO are associated with increased body weight and adiposity." (PMID 24842286, 2014). "The Fat Mass and Obesity-Associated Protein (FTO) gene rs9939609 single nucleotide polymorphism (SNP) has been associated with obesity, metabolic syndrome, insulin resistance (IR), and type 2 diabetes mellitus in the general population." (PMID 25367448, 2014). "A total of 45 SNPs located in the FTO gene showed significant associations with the obesity phenotypes." (PMID 24879436, 2014). "The FTO variants that confer a predisposition to obesity later in life appear to be associated with low weight at birth." (PMID 25539997, 2014). "During this time, variants in the FTO (fat mass and obesity associated) gene were also identified with important effects on obesity and hence, indirectly, T2D." (PMID 24744783, 2014). "The FTO rs9939609 A-allele was associated with an increased risk of obesity, with a per-allele OR of 1.23 (95% CI: 1.04, 1.46; P = 0.017) after adjusting for sex and age." (PMID 24827155, 2014). "In the present study, we tracked the associations between FTO rs9939609 and obesity-related traits from childhood into adolescence, and examined interactions of this variant with age and sex on obesity-related traits." (PMID 24827155, 2014). "Since 2007, an association between FTO single nucleotide polymorphisms (SNPs) and body mass index (BMI) and the risk of obesity had been identified in multiple populations, including adolescents and children." (PMID 24911064, 2014). "rs10767664 (BDNF) and rs3751812 (FTO) provided the strongest evidence of an association with obesity with odds ratios of 1.923 (CI: 1.32–2.81, P = 0.00072) and 1.523 (CI: 1.08–2.15, P = 0.016), respectively." (PMID 25484485, 2014). "Previous studies have found that FTO polymorphisms rs9939609, rs1421085, rs8057044 and rs8050136 were associated with the risk of obesity, type 2 diabetes and cardiovascular disease." (PMID 25251416, 2014). "The fat mass and obesity associated (FTO) gene was reported to be associated with fat deposition in Italian Duroc pigs and its inactivation can protect from obesity." (PMID 24443800, 2014). "The first SNP strongly associated with BMI and obesity was located in the FTO gene, and this has been subsequently replicated in multiple populations." (PMID 25377722, 2014).
Obesity (continued). "The fat mass and obesity associated (FTO) gene was the first obesity-related gene discovered by large-scale genome-wide association studies (GWAS), although its functional implications still need further validation." (PMID 25110886, 2014). "Single nucleotide polymorphisms (SNPs) clustered in the first intron of the fat mass and obesity‐associated (FTO) gene has been associated with obesity." (PMID 25501432, 2014). "Linear regression models were used to estimate the associations between FTO rs9939609 and obesity-related metabolic traits in the additive model." (PMID 25110886, 2014). "On the other hand, a recent study has shown that FTO rs9939609 A variant, which predisposes to obesity, has a protective effect on depression." (PMID 25265168, 2014). "First, due to a case-control study design, BMI prior to the diagnosis of tuberculosis was absent, which restricted an in-depth analysis of the ancillary effect of FTO variants on obesity." (PMID 25377722, 2014). "The A allele of rs9939609 in the FTO gene predisposes to increased body mass index (BMI) and obesity." (PMID 25265168, 2014). "The A allele of rs9939609 in the FTO (and/or other tightly linked variants) are strongly associated with BMI and obesity, also in the Polish population." (PMID 25265168, 2014). "A region spanning introns 1 and 2 of the FTO gene shows highly significant association with obesity by GWAS." (PMID 25473428, 2014). "The first GWAS-derived loci detected were intronic variants in the FTO (fat mass and obesity-associated) gene and variants approximately 200 kb downstream of MC4R." (PMID 25154910, 2014). "Evidence from epidemiological and functional studies suggests that FTO confers an increased risk of obesity by subtly changing food intake and preference." (PMID 25367448, 2014). "After exclusion of pathological situations affecting birth weight, the FTO risk allele for obesity showed a significant, inverse association with birth weight." (PMID 25539997, 2014). "Cecil and colleagues reported that the A allele of FTO rs9939609, which has been linked with obesity, was also associated with the control of food intake and food choice in children." (PMID 25251416, 2014). "In humans, variants of the fat mass and obesity associated (FTO) gene have recently been associated with obesity." (PMID 24743632, 2014). "The findings of animal studies provide evidence to support gene-environment interplay in the association between FTO and obesity." (PMID 24827155, 2014). "The risk alleles of several FTO polymorphisms located within a 47 kb linkage disequilibrium (LD) block encompassing sections of intron 1 and exon 2 of FTO have been associated with obesity and a higher BMI." (PMID 25102252, 2014). "To examine the associations between obesity-associated genetic variations in FTO and the risk of obesity in Chinese school-age population, we conducted a cross- sectional case- control study and screened obesity-associated genetic variants in FTO." (PMID 25251416, 2014). "The fat mass and obesity associated (FTO) gene plays an important role in the regulation of energy homeostasis, fat deposition and obesity." (PMID 26290716, 2014). "One recent meta-analysis suggested that the effect of FTO polymorphism on obesity-related traits in PCOS seems to be more than two times greater than the effect found in large population-based studies." (PMID 24466303, 2014). "In brief, this study found that the FTO rs9939609 variation is significantly associated with the risk of obesity and a meat-based dietary preference in Chinese Han children and adolescents." (PMID 25110886, 2014). "Gene and environment interaction studies have shown a nice association between variants in peroxisome proliferator-activated receptor gamma (PPARG), TCF7L2 and fat mass and obesity-associated protein (FTO) genes, a Western dietary pattern and T2DM." (PMID 25421534, 2014).
Obesity (continued). "Variants in the fat mass and obesity associated gene (FTO) have been studied since 2007, when it was discovered that some were associated with body mass index (BMI) and obesity." (PMID 25177340, 2014). "Recent studies have revealed that genetic polymorphisms in the fat mass and obesity associated (FTO) gene are related to human obesity." (PMID 25377722, 2014). "A study of 670 Chinese children and adolescents indicated that FTO rs9939609 was strongly associated with BMI and obesity-related metabolic traits." (PMID 25110886, 2014). "Here we used an electronic health record (EHR)-based PheWAS to explore pleiotropy of genetic variants in the fat mass and obesity associated gene (FTO), some of which have been previously associated with obesity and type 2 diabetes (T2D)." (PMID 25177340, 2014). "Subsequently, many studies have unequivocally replicated the relationship between FTO gene variants and obesity in children and adults across different populations, including Han Chinese." (PMID 25278160, 2014). "This study aims to assess the association of five FTO polymorphisms (rs9939609, rs8050136, rs1558902, rs3751812 and rs6499640) with obesity and relative parameters in Han Chinese adolescents." (PMID 24911064, 2014). "Recently, a replication study in Shanghai children aged 10–12 years confirmed associations of a single-nucleotide polymorphism (SNP) rs9939609 in FTO intron 1 with obesity indices and that this association differs in males and females." (PMID 24827155, 2014). "Several studies have evaluated the associations between some SNPs (rs9939609, rs1421085, rs8057044 and rs8050136) in FTO gene and risk of obesity and obesity-related traits in both children and adults, but the results remain inconsistent." (PMID 25251416, 2014). "Genome Wide Association Studies has identified fat-mass and obesity-associated (FTO) gene associated with obesity." (PMID 25278160, 2014). "When stratified by sex and ethnicity, FTO variants showed sex-specific and ethnic-specific effects on obesity traits." (PMID 24879436, 2014). "Among these genes, fat mass- and obesity-associated gene (FTO) stands out as the gene with the strongest significant association with obesity and it has been found to be associated with obesity in virtually all populations in which replication was attempted." (PMID 24879436, 2014). "In the sub-cohort, the associations of FTO rs9939609 with BMI (β = 1.07, P = 0.008) and obesity (OR = 2.09, 95% CI: 1.12, 3.91) were only observed 6 years later (ages 12–18 years) in girls, even after adjusting for baseline BMI." (PMID 24827155, 2014). "Around the same time as this study was published, another group also found that the FTO locus was associated with susceptibility to obesity." (PMID 24719615, 2014). "The last few years have witnessed a surge of research on the study of the physiological function and in vivo substrates of the fat mass and obesity associated (FTO) gene." (PMID 24743632, 2014). "Our previous study showed a link between the FTO gene and alcohol drinking habits among general population as well as an inverse association of the obesity associated variant with alcohol dependence." (PMID 25265168, 2014). "The fat mass and obesity-associated (FTO) gene is currently recognized as the most robust predictor of polygenic obesity." (PMID 25102252, 2014). "The critical role of these enzymes was already suggested by the identification of FTO variants as risk alleles for BMI and obesity." (PMID 24579949, 2014). "In the current study, the cross-sectional and longitudinal age-specific associations of FTO rs9939609 with BMI and the risk of obesity were examined in Chinese children and adolescents." (PMID 24827155, 2014). "In conclusion this study demonstrates that FTO deficiency has a protective effect not only on the development of obesity but also on the metabolic syndrome." (PMID 25144618, 2014).
Obesity (continued). "The association of the genetic variants of FTO gene with obesity and diabetes was recently identified by several independent GWA studies." (PMID 24877091, 2014). "For example, the well-known obesity-related FTO gene interacts with APOE which in turn, is associated with Alzheimer's disease and with MC4R, resulting in a higher chance of breast cancer." (PMID 25071839, 2014). "Recently, part of a genome-wide association study found that SNPs of the FTO were strongly associated with obesity and T2DM." (PMID 24156506, 2013). "Multiple studies have associated FTO polymorphisms with obesity in different European populations, thereby making this gene one of the most important loci implicated in polygenic obesity thus far." (PMID 23497514, 2013). "This study provides the first evidence for the association of FTO polymorphisms with anthropometric traits and risk of obesity in Portuguese children." (PMID 23342142, 2013). "Genetic variants such as the FTO A/T polymorphism studied here are associated with increased BMI and energy intake, and are thus candidates to influence obesity and other disease-related phenotypes." (PMID 23573268, 2013). "In Spanish children, dietary fat composition was found to modify the association between the FTO gene variant rs9939609 and obesity risk." (PMID 24040077, 2013). "After finding a genome-wide association with severe obesity for the FTO locus, the investigators then evaluated 12 of the known BMI-associated loci for association with severe obesity." (PMID 23950990, 2013). "The fat mass and obesity-associated (FTO) gene is an AlkB-like, Fe(II)- and 2-oxoglutarate–dependent nucleic acid demethylase that has been shown to demethylate 3-methylthymine and 3-methyluracil in single-stranded DNA and RNA, respectively." (PMID 23300482, 2013). "In a comparison with normal-weight controls, our analysis of genotype data from European adults with severe obesity attending two bariatric surgery centres has again demonstrated a strong association of the intronic FTO SNP rs9939609 with severe obesity." (PMID 23950990, 2013). "In conclusion, FTO gene, rs9939609, is associated with BMI and risk of obesity in adult Pakistani females." (PMID 24102053, 2013). "Taken together, these findings suggest that FTO variants retain an important contributory role in the pathogenesis of obesity at increasing levels of severe obesity." (PMID 23950990, 2013). "Another GWAS identified SNP rs9939609 in FTO as strongly associated with both BMI and obesity in Europeans." (PMID 24053193, 2013). "Follow-up human studies have been less clear when they sought rare variants in the FTO gene that influence obesity risk." (PMID 23360386, 2013). "A number of SNPs in tight linkage disequilibrium with rs9939609, and residing in the first intron of the FTO gene, had been associated with obesity in large populations of adults and children." (PMID 24156506, 2013). "It was reported that the fat mass and obesity associated protein, which is the genetic product of FTO, plays a role in the regulation of insulin sensitivity and insulin secretion from pancreatic beta cells." (PMID 23990951, 2013). "Several single nucleotide polymorphisms (SNPs) in the first intron of the FTO gene are associated with obesity and type 2 diabetes (reviewed)." (PMID 23300482, 2013). "Previous GWAS reports for severe adult obesity case-control samples identified associations only with SNPS within the intronic FTO locus, consistent with the robust association of these SNPs with BMI in the general population." (PMID 23950990, 2013). "Estrogen-related genes and the fat mass and obesity-associated (FTO) gene play a critical role in estrogen metabolism, and those polymorphisms are associated with a poor prognosis in breast cancer." (PMID 24065098, 2013).
Obesity (continued). "Genome-wide association study (GWAS) has identified that rs8050136 C/A polymorphism in fat mass and obesity-associated gene (FTO) was associated with the risk of type 2 diabetes (T2D) in Europeans." (PMID 24053193, 2013). "Fat mass and obesity associated (FTO) gene was found in a genome-wide association (GWA) study for T2DM and showed to predispose individuals to diabetes through an effect on Body mass Index (BMI)." (PMID 24156506, 2013). "Initially found in a GWAS of type 2 diabetes, FTO has been consistently associated with obesity and BMI in many studies." (PMID 24267414, 2013). "Hardy and colleagues took variants from the two most commonly reported obesity genes, FTO and MC4R, to see if they were associated with life course body size." (PMID 23349760, 2013). "A number of large studies replicated and confirmed the association with obesity risk in European populations and the FTO rs9939609 SNP is now recognized as one of the most important gene variants predisposing to obesity." (PMID 23306188, 2013). "In 2007, genome-wide association studies (GWAS) firstly reported that single nucleotide polymorphism (SNP) rs8050136 in fat mass and obesity-associated gene (FTO) was associated with the risk of T2D in European populations." (PMID 24053193, 2013). "The association between variants in the fat mass and obesity associated (FTO) gene on chromosome 16q12.2 and body mass index (BMI) is well-established in populations of European descent." (PMID 23341774, 2013). "While human GWAS reported FTO as the major candidate gene for the obesity associated genomic region, additional significant SNPs were located in the close neighborhood of FTO, in particular, in the RPGRIP1-like (RPGRIP1L) gene." (PMID 23691044, 2013). "SNP rs9939609 has been the common variant in the identification of FTO as the susceptibility gene to obesity and T2DM." (PMID 23840863, 2013). "Earlier studies have indicated that the fat mass and obesity-associated gene (FTO) is not only associated with BMI and weight but also with appetite and dietary intake." (PMID 23589710, 2013). "FTO variant has been studied in various Asian populations for its association with obesity, but the results of these studies are controversial in these populations." (PMID 24102053, 2013). "Several studies have reported an association between single nucleotide polymorphisms in the first intron of the FTO gene and body mass index (BMI) or obesity." (PMID 23342142, 2013). "Using genome-wide association studies (GWAS), several genes have been associated with obesity, especially the fat mass and obesity associated gene (FTO)." (PMID 24267414, 2013). "It is clear that genetic variations in the fat mass and obesity-associated (FTO) gene affect body mass index and the risk of obesity." (PMID 23835106, 2013). "For example, the FTO variant included in the GRS has been shown previously to interact with physical activity on obesity, a finding that was confirmed here, and the SEC16B variant also yielded a nominally significant interaction effect in this study." (PMID 23935507, 2013). "Genome-wide association studies (GWAS) and subsequent replication studies have identified several strongly correlated single nucleotide polymorphisms (SNPs) located in intron 1 of FTO associated with increased BMI and increased risk of obesity." (PMID 23341774, 2013). "To date, the association between FTO and obesity has been widely studied, whereas how FTO expression in the liver and hypothalamus is related to inflammation remains elusive." (PMID 24345215, 2013). "Fat mass and obesity-associated gene (FTO) has been associated with obesity, especially the common variant rs9939609." (PMID 23840863, 2013). "The FTO A/T polymorphism has initially been identified as a risk factor for obesity by two independent genome-wide association studies (GWAS)." (PMID 23573268, 2013).